ENSG00000288208 (novel protein)
Gene: Protein-coding gene on chromosome 1 (45,329,262 to 45,491,155, reverse strand). Ensembl gene ENSG00000288208.
Genetic constraint (gnomAD): Missense variants: 768 observed, 880.77 expected, observed/expected ratio (o/e) 0.87, 90% interval 0.82 to 0.93. Synonymous variants: 287 observed, 337.62 expected, observed/expected ratio (o/e) 0.85, 90% interval 0.77 to 0.94.